C2 (complement C2)
Diseases named in the same sentence as C2 in open-access papers (continued):
Sharing a sentence is not in itself a finding about the gene and the disease.
immune complex diseases (2 papers, 2013 to 2021). "In the context of a C1-INH deficiency, abnormal activation of complement via the classical pathway consumes the initial components of the cascade and may expose HAE patients to an increased risk of immune-complex disease, as seen in the C2 or C4 deficiencies." (PMID 23688356, 2013).
primary Sjögren’s syndrome (2 papers, 2020 to 2025). "Notably, mutations in the genes encoding C2, C3, C4A, C4B have been linked to SLE, and Sjogren’s syndrome has been reported in patients with genetic deficiencies in C1q, C4, and C2." (PMID 32514272, 2020).
prion disease (2 papers, 2021 to 2022). A transmissible disease that is caused by a protein that is able to induce abnormal folding of normal cellular proteins, leading to characteristic spongiform brain changes, which are associated with neuronal loss without an inflammatory response. "For example, inhibiting the down-stream of complement cascade (C5 and MAC) and/or C5aR could protect the brain from Plasmodium infection-induced tissue damage, whereas inhibition restricted to the upstream components (C1q, C2, and FB) could be beneficial in prion diseases, as shown in animal models." (PMID 34408631, 2021).
retinal degeneration (2 papers, 2021 to 2023). Degeneration of the retina. "Three genes (Tpm2, Myh11, Tagln) may be related to cellular filaments, and Mdk (midkine) and C2 (complement C2) are connected to retinal degeneration and AMD, respectively." (PMID 34404875, 2021). "The real-time RT-PCR was conducted to examine the expression of complement genes (C1q, C2, C3, C4, CFI and CFD) in the guinea pig model of long-term form deprivation-induced myopic retinal degeneration." (PMID 37448698, 2023).
retinal disease (2 papers, 2021). "In addition, other retinal disease-causing genes related to AMD were mainly expressed in clusters P4, P6 and P7, but some susceptibility genes, such as C2, FBLN5, and TLR4, were highly expressed in the macular cluster." (PMID 34977041, 2021).
type 2 diabetes (2 papers, 2024). "Studies have revealed that high levels of complement C2 in the blood plasma are linked with an increased risk of type 2 diabetes." (PMID 39449501, 2024).
Achalasia (1 paper, 2023). A disorder of esophageal motility characterized by the inability of the lower esophageal sphincter to relax during swallowing and by inadequate or lacking peristalsis in the lower half of the body of the esophagus. "In the current study, complement C1q, C1s, C2, C3, C4-A, C4-B, C5, C6, and C9 were all upregulated in the achalasia group." (PMID 37324545, 2023).
Arthritis (1 paper, 2020). Inflammation of a joint. "Thus NAb C2-IgM specifically binds to apoptotic cells, rationalizing its study for enhancement of arthritis or its incorporation as a component of an scFv-linked complement inhibitor to deliver complement inhibition activity to injured cells or tissues." (PMID 33178202, 2020). "First to show that C2 mAb by itself, in mice, can enhance injury, i.e., arthritis, we used the mouse model of CAIA, which is dependent on the CS for it is involved in the effector phase of the arthritis." (PMID 33178202, 2020). "However, C2 scFv alone should not demonstrate a substantial effect on arthritis because it lacks the Fc domain and, therefore, will not activate complement." (PMID 33178202, 2020).
autoimmune thyroid disease (1 paper, 2023). Inflammatory disease of the thyroid gland due to autoimmune responses leading to lymphocytic infiltration of the gland. "According to enrichment analysis, C1 marker genes were enriched in the adherens junction and proteoglycans, while C2 marker genes were enriched in antigen processing and presentation, autoimmune thyroid disease, and other inflammation-related pathways." (PMID 36941725, 2023).
bladder cancer (1 paper, 2019). "C-2 exhibits cytotoxic effect on bladder cancer cells, and JNK activated by C-2 triggers autophagy and up-regulates SQSTM1/p62 proteins, contributing to activation of Nrf2 pathway." (PMID 31685029, 2019).
Brain atrophy (1 paper, 2024). Partial or complete wasting (loss) of brain tissue that was once present. "Preliminary analyses in different cognitive groups demonstrated that the reduced CSF complement peptides C1q, C2, C5, and CFB were associated with longitudinal brain atrophy (i.e., ventricles, whole brain, middle temporal lobe, or fusiform gyrus) and cognitive decline in MCI participants." (PMID 38238858, 2024).
C3 glomerulopathy (1 paper, 2022). "Conversely, the p.Q263P variant found in a patient with C3 glomerulopathy resulted in the loss of C2 function." (PMID 36591303, 2022).
cognitive decline (1 paper, 2024). "This study systematically investigated the association of CSF complement proteins (C1q, C2, C5, C6, C8B, and CFB) with cognitive decline, AD pathology and brain structures, as well as the mediation effects of regional brain structures on cognition." (PMID 38238858, 2024). "Besides, our study found that neuroimaging markers might mediate the associations between CSF complement proteins (C1q, C2, C5, CFB and clusterin) and cognitive decline." (PMID 38238858, 2024). "The direct impact of reduced CSF complement peptides C1q, C2, C5, and CFB on cognitive decline was also observed in the MCI participants." (PMID 38238858, 2024).
colorectal tumors (1 paper, 2020). "Gain in the MYC gene was seen throughout the cancer type, and c2 was uniquely characterized by loss of the chromosome 20 p-arm, which harbors the hsa-mir-103–2 previously reported to be downregulated in colorectal tumors." (PMID 33272320, 2020).
complement component 2 deficiency (1 paper, 2024). "In IRD1, the monoallelic c.841_849 + 19del variant in the C2 gene is associated with complement component 2 deficiency through skipping of exon 6 during RNA splicing." (PMID 38956727, 2024).
dementia (1 paper, 2026). Loss of intellectual abilities interfering with an individual's social and occupational functions. "A higher mass spectrometry signal that maps to both complement c2 and complement factor B proteins was associated with lower hazard for incident dementia (hazard ratio = 0.75, p < 3.1 x 10-4, ncases = 212 and ncontrols = 6,765) diagnosed up to 17 years after blood sampling." (PMID 41646675, 2026).
diabetic foot (1 paper, 2025). A diabetic foot is a foot that exhibits any pathology that results directly from diabetes mellitus or any long-term (or "chronic") complication of diabetes mellitus. "Ro/e analysis and UMAP plots further visualized the distribution of these subpopulations, revealing that C2 was most highly expressed in recovered diabetic foot patients (DFUHealer), while C4 was most highly expressed in diabetic patients without diabetic foot (nonDFUDiabetic)." (PMID 40612951, 2025).
diabetic nephropathy (1 paper, 2023). "In diabetic nephropathy, we identified positive correlations specifically with complement components C2 and C5 and receptors C5AR2 and CR2." (PMID 38069385, 2023).
Encephalocele (1 paper, 2024). A neural tube defect characterized by sac-like protrusions of the brain and the membranes that cover it through openings in the skull. "Surprisingly, all E13.5 embryos with just the C1Δ deletion recapitulated the encephalocele phenotype observed in C1-C4Δ, while C2-C4Δ mutants did not display any phenotype." (PMID 39372737, 2024).
endometritis (1 paper, 2023). An acute or chronic, usually bacterial infectious process affecting the endometrium. "Specific mRNA expression patterns of C3, C2, LTF, PF4, and TRAPPC13 are present in the blood and endometrium of dairy calves with subclinical endometritis." (PMID 37756095, 2023).
glioblastoma (1 paper, 2016). The most malignant astrocytic tumor (WHO grade IV). "The natural Clostridium botulinum C2 toxin was then delivered to human glioblastoma A172 and synchronized HeLa cells." (PMID 27025362, 2016).
glomerulopathy (1 paper, 2021). "We now report the identification of the same mutation and another C2 GoF mutation R249C in two other patients with a glomerulopathy of uncertain etiology." (PMID 34899688, 2021).
gout (1 paper, 2021). A condition characterized by painful swelling of the joints, which is caused by deposition of urate crystals. "Further work needs to be done to establish how C8B and Complement C2 regulate gout process by complement and coagulation cascades." (PMID 34635120, 2021).
heart failure (1 paper, 2025). Inability of the heart to pump blood at an adequate rate to meet tissue metabolic requirements. "Heart failure scores were elevated in C0 NAP1L1+ TCs (G1), C0 NAP1L1+ TCs (G2/M), C0 NAP1L1+ TCs (S), C2 MKI67+ TCs (G2/M), and C2 MKI67+ TCs (S)." (PMID 40842994, 2025).
hyperandrogenism (1 paper, 2023). Excessive secretion of androgens from the adrenal glands or gonads. "However, there was an increase in C2, associated with lectin pathway activation, in obese PCOS that was not seen in the nonobese cohort and that did not associate with BMI, hyperandrogenism or insulin resistance, suggesting that an additional unaccounted for factor may be involved." (PMID 37566081, 2023).
ischemia reperfusion injury (1 paper, 2020). Adverse functional, metabolic, or structural changes in ischemic tissues resulting from the restoration of blood flow to the tissue (reperfusion), including swelling; hemorrhage; necrosis; and damage from free radicals. "In the recent past, we have cloned and purified one IgM NAb, designated C2, a mAb that recognizes an epitope expressed on a subset of phospholipids (PL), and shown that C2 mAb specifically bind to the intestine, brain, and heart following ischemia-reperfusion injury." (PMID 33178202, 2020).
leprosy (1 paper, 2019). Leprosy is a chronic infectious disease affecting primarily the skin and peripheral nervous system. "The higher frequency of the combination of KIR2DS5 activating gene with its C2 ligand (KIR2DS5/C2+) was associated with MB leprosy patients when compared to healthy subjects (29.6% vs. 21.8%, P = 0.048, adjusted OR = 1.50, 95% CI = 1.02–2.21)." (PMID 31525196, 2019).
liver cancer (1 paper, 2023). An epithelial or non-epithelial malignant neoplasm that arises from the liver. "In addition, the mRNA levels of Galectin-1 were significantly increased after co-transfection of C2/c-Jun and C2/ATF2 in liver cancer cells." (PMID 37215991, 2023).
lung adenocarcinoma (1 paper, 2023). A carcinoma that arises from the lung and is characterized by the presence of malignant glandular epithelial cells. "In a similar manner, expression of C2, IFI30 and TUBB4 was negatively associated with the disease outcome in lung adenocarcinoma compared to other carcinomas." (PMID 37784035, 2023).
lymphoma (1 paper, 2023). A malignant (clonal) proliferation of B- lymphocytes or T- lymphocytes which involves the lymph nodes, bone marrow and/or extranodal sites. "When added to human serum and reacted with lymphoma cells opsonized with the type I anti-CD20 mAbs rituximab and ofatumumab, the recombinant triple C2 mutant formed convertases of higher activity and extended stability compared to those built from the wild-type C2 protein." (PMID 38201478, 2023).
Motor axonal neuropathy (1 paper, 2022). Progressive impairment of function of motor axons with muscle weakness, atrophy, and cramps. "In parallel studies, C2 inhibition also protects axonal integrity in our well-established model of acute motor axonal neuropathy mediated by both mouse and human anti-GM1 antibodies." (PMID 36523267, 2022).
myopia (1 paper, 2023). "When comparing the aqueous humour complement levels between the two groups, all components of the CP (C1q, C2, C4 and C4b) and the common pathway (C3, C3b/iC3b and C5) were significantly higher in the high-myopia group." (PMID 37448698, 2023). "Previous studies have reported the upregulation of the complement pathway, including C1q, C1qa, C2 and C1qb during the development stages of myopia in guinea pigs and chicks." (PMID 37448698, 2023). "In this study, we detected significantly higher intraocular levels of complement proteins involved in the classic pathway (C1q, C2, C4 and C4b) and alternative pathway (CFB, CFI, C3b/iC3b) in human eyes with high-myopia or with pathological myopia." (PMID 37448698, 2023).
nephritis (1 paper, 2025). Inflammation of renal tissue. "We could not verify that low GCN was associated with age at nephritis onset (data not shown), and no data on C2 deficiency were available for this cohort." (PMID 40280868, 2025).
neuroblastoma (1 paper, 2023). Neuroblastoma (NB) is the most common solid, extracranial childhood tumor. "To test whether PS-specific C2 fusion proteins are suitable for detecting the exposure of PS on the plasma membrane of cells in vitro, we induced apoptosis in the culture of two different cell lines: mouse neuroblastoma Neuro2a and human embryonic kidney HEK293T cells." (PMID 37501184, 2023).
Osteopenia (1 paper, 2025). Osteopenia is a term to define bone density that is not normal but also not as low as osteoporosis. "In summary, our research indicates that OPC may serve as a potential therapeutic candidate by targeting and regulating C2 NR4A1+ MSCs in osteopenia, thereby playing a role in the prevention and treatment of OP." (PMID 41262236, 2025).
osteosarcoma (1 paper, 2021). A usually aggressive malignant bone-forming mesenchymal neoplasm, predominantly affecting adolescents and young adults. "Exosomes extracted from the serum of osteosarcoma canine patients contain possible prognostic indicators such as: Tetranectin, as well as Complement C2 and C3 proteins." (PMID 33933069, 2021).
Peritoneal Fibrosis (1 paper, 2022). Disorder characterized by a wide range of structural changes in PERITONEUM, resulting from fibrogenic or inflammatory processes. "We demonstrate that the gene expression of the complement molecules (C2, C3, C5, C6) and the inhibitory molecules (CD55) is increased in the abdominal wall of the CHX-induced mouse model of peritoneal fibrosis." (PMID 36359246, 2022).
Polypoidal choroidal vasculopathy (1 paper, 2014). The presence of aneurysmal 'polypoidal' lesions in the choroidal vasculature. "The aim of this study was to clarify whether complement component 2 (C2) and complement factor B (CFB) genotypes are associated with subtypes of polypoidal choroidal vasculopathy, such as polypoidal CNV and typical PCV." (PMID 24965207, 2014).
pregnancy disorder (1 paper, 2016). A disorder that is related to pregnancy. "The presence of maternal KIR AA haplotype, constituted by inhibitory KIRs genes only, is associated with pregnancy disorders but the risk of pre-eclampsia is increased when the fetus presents more C2 genes than the mother or when it carries a paternal HLA-C2 epitope." (PMID 28082990, 2016).
psychosis (1 paper, 2024). "C4B, Complement C4-A (C4A), Complement C2 (C2), A2M, LRG1, and the Fibrinogen alpha, beta, and gamma chains (FGA, FGB, and FGG) were differentially expressed between those who transitioned to psychosis and those who did not, adjusting for age, sex, and study." (PMID 38243809, 2024).
rheumatoid arthritis (1 paper, 2014). A chronic, systemic autoimmune disorder characterized by inflammation in the synovial membranes and articular surfaces. "Although it is a multifactorial disease, there is an overwhelming clinical evidence showing that homozygous deficiency in any of the classical pathway proteins – C1q, C1r, C1s, C4, and C2 – predisposes an individual to develop SLE and other autoimmune diseases such as rheumatoid arthritis (RA)." (PMID 25018754, 2014).
Salmonella Infections (1 paper, 2020). Infections with bacteria of the genus SALMONELLA. "c2-HDA is capable of inhibiting SPI1-encoded invasion gene expression at very low concentration and may thus be further investigated as an inhibitor of Salmonella infection." (PMID 32690633, 2020).
sarcopenia (1 paper, 2026). Progressive decline in muscle mass due to aging which results in decreased functional capacity of muscles. "We identified seven robust protein signatures (LRG1, CST3, TIMP1, C2, ITIH1, AMBP and LYZ) that showed consistent significant associations with sarcopenia components in both cohorts." (PMID 41782349, 2026).
sinusitis (1 paper, 2012). An acute or chronic inflammatory process affecting the mucous membranes of any sinus cavity. "Another work showed relative high but non-statistically tested occurrence of severe and minor infections – including recurrent sinusitis – in patients with C2 deficiencies." (PMID 23144819, 2012).
steatosis (1 paper, 2022). Increased lipid within the cytoplasm of cells. "The expression of C1qa, C1qb, C1qc, and C2 in KCs was significantly higher in patients with severe steatosis when compared to healthy controls." (PMID 36304458, 2022).
thyroid disease (1 paper, 2018). "We have additionally identified C2 and C4a, a short-lived fragment of C4, in our data, which indicates a higher probability for involvement of the classical and lectin complement pathways in thyroid disease that are activated through antibody-independent pathways." (PMID 29301248, 2018).
ZIKV infection (1 paper, 2023). "Interestingly, results show induction of components of the complement system that were common to both DENV and ZIKV in the brain such as CfB and C3, but C2 and C4a—components of the classical and lectin pathways, were only induced by ZIKV infection." (PMID 37022660, 2023).